NEDD4L (NEDD4 like E3 ubiquitin protein ligase)
Diseases named in the same sentence as NEDD4L in open-access papers (continued):
Sharing a sentence is not in itself a finding about the gene and the disease.
cancer (continued). "Similarly, shNEDD4L cells were sensitized to pharmacological inhibition of ULK1 or ASCT2, as well as to the blockade of mitochondrial OXPHOS when compared to shCTL cells, suggesting that NEDD4L-knockdown cancer cells rely on mitochondrial metabolism to sustain cell growth and survival." (PMID 31959741, 2020). "Additionally, investigating potential therapeutic interventions that target NEDD4L or its downstream effectors could pave the way for novel treatments in cancer therapy, not limited to ESCC but potentially applicable to other cancers with dysregulated ferroptosis pathways." (PMID 39557844, 2024). "We found that DEGs, such as CDKN1C, NEDD4L, PLK2 and SOX4, were closely related to the occurrence and development of malignant tumors." (PMID 38520027, 2024). "Lactotransferrin (LTF) is a protein that binds directly to NEDD4L, and NEDD4L-targeted degradation of LTF inhibits iron accumulation and subsequent iron-related death in various cancer cells." (PMID 38027016, 2023). "One study showed that NEDD4L-mediated degradation of LTF inhibited intracellular iron accumulation and subsequent oxidative damage-mediated ferroptosis in various cancer cells." (PMID 38027016, 2023). "As a result, NEDD4L was negatively correlated to EGFR mRNA and protein levels in cancer tissues in the TCGA_LUAD dataset." (PMID 35090513, 2022). "The β-arrestin promotes the formation of the GCN2-β-arrestin-NEDD4L complex by binding NEDD4L to GCN2, enabling ubiquitin-mediated GCN2 degradation and thereby preventing cancer." (PMID 36293239, 2022). "Regarding LTF, an iron-binding transport protein, degradation by NEDD4L prevents intracellular iron accumulation and subsequent oxidative-damage-mediated ferroptosis cell death in PANC-1 cancer cells." (PMID 36293239, 2022). "The results revealed that NEDD4L and HECW2 were significantly downregulated while HECW1 was significantly upregulated in cancer tissues compared with normal tissues." (PMID 35090513, 2022). "Therefore, targeting NEDD4L with these compounds might be helpful for cancer therapy in the future." (PMID 34869021, 2021). "The DSS forest diagram is used to illustrate the correlation between NEDD4L gene expression and DSS in various cancer types in the TCGA database." (PMID 34539897, 2021). "And as well as the down-regulation of NEDD4L and the up-regulation of UBE2T in LUAD were independently confirmed using the cancer genome atlas (TCGA) database." (PMID 34838005, 2021). "Conversely, pre-stimulation of NK-92 cells transfected with the WT promoter sequences of NEDD4L using the ferroptosis inducer FIN56, or transfection with NEDD4L promoter sequences containing AAAGGGGTCT deletion, diminished the anti-cancer efficacy of the WT promoter sequences." (PMID 40399270, 2025). "Taken together, these results indicated that miR-629-5p may play a critical role in KSRP-regulated NEDD4L mRNA stability and subsequent EMT-induced cancer progression." (PMID 37580757, 2023). "A systematic search in different electronic databases indicated that, among HECT-type E3 ligases, members of the NEDD4 family including NEDD4-1, NEDD4L, SMURF-1, SMURF-2, WWP1, WWP2, and ITCH have been investigated in many various cancers with defective autophagy, as reviewed in next sections." (PMID 36918822, 2023). "We found that AMPK plays a role in phosphorylating and stabilizing NEDD4L in NSCLC, which may be due to the heterogeneity of different cancer types." (PMID 37240137, 2023). "However, NEDD4L reportedly mediated GCN2 ubiquitination and subsequent proteasomal degradation, which prohibited cancer cell apoptosis." (PMID 38027016, 2023). "Next, we examined NEDD4L protein levels in LUAD tissues and para-carcinoma tissues using IHC." (PMID 35090513, 2022). "Concurrently, the amount of knowledge that remains to be uncovered on the NEDD4L subgroup, as well as other members of the broader HECT family, provide many opportunities for the generation of novel therapeutics to treat a broad range of cancers." (PMID 33869064, 2021).
cancer (continued). "Thus, we proposed that NEDD4L can inhibit Akt activation in ccRCC possibly through degrading its upstream activators such as STK35, SphK2, CTR1, and PIK3CA, which were previously reported in different cancers." (PMID 37580757, 2023). "Neural precursor cell-expressed developmentally downregulated gene 4 L (NEDD4L, also called NEDD4-2), which is identified as a HECT-type E3 ubiquitin ligase, is involved in the regulation of multiple substrates and mediation of drug sensitivity in diverse cancers." (PMID 35236820, 2022). "Therefore, the mechanisms that NEDD4L- and HIF-1α- mediated regulation of GC progression need to be explored further, which may ultimately promote the development of new anti-cancer strategies." (PMID 31673244, 2019). "Thus, the role of NEDD4L in cancer progression is complex and not yet fully understood." (PMID 31959741, 2020). "Among 14 paired cancer tissues, negative or low protein expression of CPNE1 was detected in 4 samples, and high expression was detected in 10 samples, while 57% were negative for NEDD4L expression and the rest were positive." (PMID 34743202, 2021).
infection (8 papers, 2016 to 2024). The state of being infected such as from the introduction of a foreign agent such as serum, vaccine, antigenic substance or organism. "We previously found that NEDD4L levels steadily increased during infection and demonstrated that NEDD4L strongly interacts with TRP120 and facilitates TRP120 ubiquitination in vitro." (PMID 34451426, 2021). "We have demonstrated that NEDD4L is a HECT E3 Ub ligase that is upregulated during infection, colocalizes with ehrlichial morulae, and interacts and ubiquitinates TRP120." (PMID 29376035, 2017). "We demonstrate that multiple species of mono- and polyubiquitinated TRP32 can be detected during infection, and that the host E3 enzyme, NEDD4L, ubiquitinates TRP32." (PMID 29376035, 2017). "During infection, we determined that TRP32 interacts with NEDD4L and can be ubiquitinated by NEDD4L in vitro." (PMID 29376035, 2017). "Although expression of this transcript peaked at 72 hr of infection, it was nevertheless clearly detectable at early time points, suggesting that UL42 protein is likely to be expressed contemporaneously with degradation of NEDD4 and NEDD4L." (PMID 31873071, 2019). "NEDD4L precipitated with TRP32, suggesting an interaction during infection." (PMID 29376035, 2017). "Multiple mono- and polyubiquitinated forms of TRP32 were detected during infection, including some which did not completely disappear when cells were treated with the NEDD4L inhibitor." (PMID 29376035, 2017).
kidney disease (6 papers, 2020 to 2025). "A previous study showed that mice deficient in NEDD4L, specifically in the renal tubules (Nedd4L Ksp1.3), developed mild kidney disease due to the upregulation of ENaC." (PMID 38755664, 2024). "Given the growing association of NEDD4L variants and expression levels with human kidney diseases, this study sheds understanding on how known signaling pathways may be aberrantly regulated in disease and provides a novel potential diagnostic and therapeutic target." (PMID 33854040, 2021).
cardiovascular disease (4 papers, 2022 to 2025). "In the past few years, the association between Nedd4L and cardiovascular diseases has been focused by many investigators." (PMID 35429991, 2022). "Many previous studies established the association of NEDD4L with cardiovascular disease." (PMID 38526036, 2024). "NEDD4L is an E3 ligase with an HECT domain that is involved in the pathogenesis of cardiovascular diseases through multiple pathways." (PMID 40943126, 2025). "Recently, the relationship between NEDD4L and cardiovascular diseases has garnered significant attention." (PMID 40943126, 2025). "This review aims to summarize the progress and mechanism of Nedd4L in cardiovascular diseases, and provide potential perspective for the clinical treatment or prevention of related cardiovascular diseases by targeting Nedd4L." (PMID 35429991, 2022). "In conclusion, Nedd4L, as the dominating E3 ligase of the Nedd4 family, and related signaling play fundamental roles in cardiovascular diseases." (PMID 35429991, 2022). "Nedd4L is widely expressed during mouse development and is also involved in the pathogenesis of cardiovascular diseases through multiple pathways." (PMID 35429991, 2022). "In this article, we summarized the recent progress on the role of Nedd4L in various cardiovascular diseases." (PMID 35429991, 2022). "In this present review, we’ve already known that the ubiquitination ligase, Nedd4L, participates in various pathophysiological processes of cardiovascular diseases." (PMID 35429991, 2022). "These authors utilized high-fat diet (HFD)-induced Apolipoprotein (Apo) E −/− mice and raw macrophages transfected with NEDD4L to evaluate whether NEDD4L counteracts atherosclerotic cardiovascular disease occurrence." (PMID 40136477, 2025).
neurodegenerative disease (4 papers, 2016 to 2023). A disorder of the central nervous system characterized by gradual and progressive loss of neural tissue and neurologic function. "NEDD4L-mediated COX4 degradation promotes OS and the development of neurodegenerative diseases." (PMID 38127902, 2023).
bacterial infection (3 papers, 2021 to 2025). "Nedd4L is an important regulator of inflammatory responses, playing significant roles in both influenza virus and bacterial infections." (PMID 39065060, 2024). "NEDD4L-deficient cells showed increased GSDM activation, IL-1β release and were significantly more susceptible to cell death induced by NLRP3 agonists, cytotoxic agents, and bacterial infection." (PMID 41261204, 2025).
metabolic disorder (3 papers, 2021 to 2024). "The decreased expression of NEDD4L may lead to metabolic disorder and promote the development of ccRCC." (PMID 34458018, 2021).
cardiac diseases (2 papers, 2020 to 2023). "These included the voltage gated calcium channel unit mentioned earlier, Cacna1d, as well as a key cardiac ubiquitin ligase, Nedd4l, which regulates sodium channel activity, with its mutations involved in various cardiac diseases including DCM." (PMID 37110207, 2023). "Among the nine members of the NEDD4 family, NEDD4-1, NEDD4L, ITCH, WWP1, WWP2, SMURF1 and SMURF2 are involved in heart diseases." (PMID 33110392, 2020).
blood disorders (1 paper, 2021). "Genes also implicated in blood disorders, including Bcl11a, Nedd4l, and Aspn, with common pathways involved in regulation of blood pressure, protein modifications, transforming growth factor regulation, and negative regulation of developmental pathways were identified." (PMID 34075076, 2021).
digestive diseases (1 paper, 2024). "In recent years, the relationship between NEDD4/NEDD4L and digestive diseases has become a hotspot research topic." (PMID 38785984, 2024). "In this paper, we reviewed the roles of NEDD4 and NEDD4L in various digestive diseases for the purpose of providing new strategies for the prevention and treatment of digestive diseases." (PMID 38785984, 2024). "Specifically, NEDD4 and NEDD4L, as the major E3 ligases of the NEDD4 family, are critical in a variety of pathophysiological processes in digestive diseases and are involved in disease development by mediating the ubiquitination degradation of PTEN, c-Myc, and P21." (PMID 38785984, 2024).
infectious disease (1 paper, 2025). A disorder directly resulting from the presence and activity of a microbial, viral, or parasitic agent in humans. "NEDD4L is a component of several pathways related to immunity such as infectious disease and innate immune system pathways." (PMID 40678382, 2025).
NEDD4L also shares sentences with these, for which no sentence is quoted: chronic kidney disease (6 papers); lung disease (4); essential hypertension (3); polymicrogyria (3); restrictive lung disease (3); Seizure (3); acute lung injury (2); acute myocardial infarction (2); autism (2); benign prostatic hyperplasia (2); breast invasive carcinoma (2); cardiac arrhythmias (2); cholangiocarcinoma (2); cleft palate (2); colon adenocarcinoma (2); diabetic retinopathy (2); edema (2); end-stage renal disease (2); epileptic encephalopathies (2); fibrosis (2); fragile X syndrome (2); Hypercalciuria (2); hyperglycaemia (2); hypospadias (2); ischemic disease (2); liver cancer (2); metastasis (2); movement disorder (2); neurodevelopmental disorder (2); neurological diseases (2).
A further 77 diseases each share a sentence with NEDD4L in 2 papers or fewer.